LINC00237 (long independently transcribed non-coding RNA 237)
Synonyms: NCRNA00237
Gene: Long non-coding RNA gene on chromosome 20 (21,057,376 to 21,106,581, reverse strand). Ensembl gene ENSG00000225127.
Diseases named in the same sentence as LINC00237 in open-access papers:
LINC00237 is named in the same sentence as 1 disease in open-access papers, as found by Europe PMC text mining. Sharing a sentence is not in itself a finding about the gene and the disease. The quoted sentences say what the papers report.
glioma (1 paper, 2022). A benign or malignant brain and spinal cord tumor that arises from glial cells (astrocytes, oligodendrocytes, ependymal cells). "The forest plot shows that EPB41L4A.AS1, GDNF.AS1, HAR1A, LINC00237, SLC25A21.AS1, SNA13.AS1, and WDFY3.AS2 are the protective factors with HR < 1, while LINC00092, LINC00265, LINC00339, LINC00665, PAXIP1.AS2, SNHG16, SNHG9 and SOCS2.AS1 are risk factors with HR>1 in glioma patients." (PMID 35273128, 2022).